LINC00092 (long independently transcribed non-coding RNA 92)
Synonyms: bA346B7.1; NCRNA00092; LOC105376159
Gene: Long non-coding RNA gene on chromosome 9 (96,019,724 to 96,028,033, reverse strand). Ensembl gene ENSG00000225194.
Diseases named in the same sentence as LINC00092 in open-access papers:
LINC00092 is named in the same sentence as 7 diseases in open-access papers, as found by Europe PMC text mining. Sharing a sentence is not in itself a finding about the gene and the disease. The quoted sentences say what the papers report.
ovarian carcinoma (6 papers, 2018 to 2025). A malignant neoplasm originating from the surface ovarian epithelium. "LINC00092 is overexpressed in metastatic ovarian cancer and is related to the invasion and migration of ovarian cancer cells and poor prognosis; in addition, it can also be used as a diagnostic molecular biomarker for colon adenocarcinoma." (PMID 34615480, 2021). "CAFs-secreted CXCL14 induces LINC00092 upregulation which promotes ovarian cancer metastasis by enhancing PFKFB-2 translation." (PMID 31448238, 2019). "The role of LINC00092 in ovarian cancer aggressiveness has been demonstrated." (PMID 35222443, 2022). "Linc00092 is upregulated in response to the chemokine in ovarian cancer cells." (PMID 29752439, 2018). "A previous study shown that LINC00092, activated by CXCL14-rich CAFs, drives ovarian cancer metastasis by modulating glycolysis via PFKFB2 interaction, underscoring a vital metabolic feedback loop between CAFs and cancer cell advancement." (PMID 39988592, 2025). "This study highlights a reciprocal feedback loop mediated by LINC00092 between CXCL14-positive CAFs and ovarian cancer cells that is crucial for promoting the metastatic behavior of ovarian cancer." (PMID 35842651, 2022). "LINC00092 interacted with a glycolytic enzyme named 6-phosphofructo-2-kinase/fructose-2,6-biphosphatase 2 (PFKFB2) to modulate glycolysis levels and supportive function of CAFs, thereby facilitating ovarian cancer metastasis." (PMID 35222443, 2022).
breast carcinoma (2 papers, 2021 to 2024). "The LINC00092 has been reported to interact with PC to modulate glycolysis and oxidative stress of breast cancer cells, a novel biological mechanism by which noncoding RNA association with PC regulates cancer metabolism." (PMID 38081642, 2024). "Lower LINC00092 expression was shown to be related to favorable prognosis for patients with colon adenocarcinoma or breast cancer, and a poorer prognosis for patients with lung adenocarcinoma." (PMID 34930244, 2021).
glioma (2 papers, 2021 to 2022). A benign or malignant brain and spinal cord tumor that arises from glial cells (astrocytes, oligodendrocytes, ependymal cells). "Results show the mean expression levels of LINC00665, LINC00339, SNHG16, PAXIPI.AS2 and LINC00092 in the glioma tissues are higher than those in the NBTs." (PMID 35273128, 2022). "The forest plot shows that EPB41L4A.AS1, GDNF.AS1, HAR1A, LINC00237, SLC25A21.AS1, SNA13.AS1, and WDFY3.AS2 are the protective factors with HR < 1, while LINC00092, LINC00265, LINC00339, LINC00665, PAXIP1.AS2, SNHG16, SNHG9 and SOCS2.AS1 are risk factors with HR>1 in glioma patients." (PMID 35273128, 2022). "Among these, there were six lncRNAs (TTC28-AS1, AC090425.1, GUSBP11, LINC00092, HCG18, and FAM95B1) that have not been studied in gliomas, and we visualize the Kaplan–Meier analysis results (p < 0.05)." (PMID 34615480, 2021).
breast tumors (1 paper, 2018). "Another analysis of TGCA RNA-seq data of human breast tumors identified a decreased expression of LINC00092 and C2orf71 as associated with poor prognosis, and identified a putative network of coexpression of LINC00092 with mRNAs RGMA and SFRP1 that were regulated by miR-449a and miR-452-5p." (PMID 30545127, 2018).
cancer (7 papers, 2018 to 2025). A tumor composed of atypical neoplastic, often pleomorphic cells that invade other tissues. "Regarding the up-regulated lncRNAs, only a low number of them have been previously implicated in cancer, such as the up-regulated CASC15, LINC00662, LINC01272, LINC00857, LINC00092, LINC00673 and the down-regulated LINC00657, LINC01087 and LINC00993." (PMID 32753692, 2020). "LINC00092 expression is modulated in the response to CXCL14, a chemokine secreted by cancer-associated fibroblasts (CAFs) linked to metastasis." (PMID 31191327, 2019). "Therefore, LncRNA-CAF and LINC00092 were served as significant modulators of feedback loop in the cancer cells and CAFs, which were critical for the progression of cancer." (PMID 31448238, 2019). "Also, the PFKFB2-induced glycolytic cancer cell phenotype seems critical for the maintenance of CXCL14 secretion from CAFs, suggesting for LINC00092 a regulatory feedback loop between cancer cells and CAFs that is important for the maintenance of the tumor microenvironment." (PMID 31191327, 2019). "We found that AC090425.1 and HCG18 were related to a variety of cancer-related pathways, while TTC28-AS1 and LINC00092 were related to diverse cancer functions." (PMID 34615480, 2021).
LINC00092 also shares sentences with these, for which no sentence is quoted: colon adenocarcinoma (2 papers); lung adenocarcinoma (1).